INS (insulin)
Diseases named in the same sentence as INS in open-access papers (continued):
Sharing a sentence is not in itself a finding about the gene and the disease.
Hypertension (continued). "Jiaodavirus was positively correlated with proinflammatory activity (IL-18, IL-10, MCP-1), IR (HOMA-IR and insulin levels), and hypertension (DBP percentile)." (PMID 37342535, 2023). "The Mediterranean diet, DASH diet (Dietary Approaches to Stop Hypertension) and low glycemic index diet seem to be the healthiest dietary approaches that have the strongest relationship with greater insulin sensitivity among PCOS women." (PMID 37432289, 2023). "A prospective cohort study demonstrated higher levels of fasting serum insulin and HOMA-IR were associated with hypertension in women whereas hypertension in men." (PMID 36717862, 2023). "An upregulated mTORC1/S6K1 activity contributes to deregulated insulin-stimulated vasodilation by suppressing eNOS (endothelial nitric oxide synthase), resulting in vasoconstriction and hypertension." (PMID 37894760, 2023). "Rates of insulin use, daily glycemic monitoring and treatment for systemic hypertension were 68.4%, 70.2% and 70.2%, respectively." (PMID 37430345, 2023). "The mechanism of RC-induced hypertension is not fully clarified, potentially involving vascular damage, oxidative stress, inflammation, insulin resistance and the renin-angiotensin system, while the role of hypertension in stroke has been well recognized." (PMID 37304024, 2023). "The results of semiparametric regression model revealed that being male, hypertension, insulin treatment, and frequency of clinical visits had a significant linear relationships with the odds of having DR." (PMID 36624377, 2023). "Overall, both SGLT2-I users and GLP1-RA users appeared to suffer more from comorbidities (hypertension, hyperlipidaemia, retinopathy, neuropathy) compared to SU users, and insulin use was higher in these two groups." (PMID 37386427, 2023). "A recent study highlighted the involvement of AGT (rs699) in insulin sensitivity, while AGT rs4762 and rs699 have shown significant associations with hypertension in several ethnic populations." (PMID 37693342, 2023). "Elevated levels of insulin contribute to increased sodium reabsorption, renin excretion, and sympathetic activity, ultimately leading to high blood pressure." (PMID 37693342, 2023). "Reaven introduced the concept of “Syndrome X” and defined it as a cluster of disturbances in glucose and insulin metabolism, dyslipidemia, and hypertension (HTN)." (PMID 37876536, 2023). "The dysfunctional interaction of ECs, muscle growth factors and insulin resulting from IR, and the loss of appropriate signaling, precipitate alterations in the MVU myocyte function that underpin vascular dysfunction/high blood pressure and T2DM." (PMID 37445602, 2023). "In children with hypertension, FM correlated significantly with insulin levels, urate, serum creatinine, lipid fractions, vitamin D and microalbuminuria as well with hepatic steatosis, systolic blood pressure and left ventricular hypertrophy." (PMID 35626780, 2022). "The DKD patients were more like to be older, to have hypertension, to have a higher serum triglyceride level, a higher level of calcium, and a higher level of insulin." (PMID 36323795, 2022). "In males, the variables with downtrend relative to increasing SMI quartiles were age, BMI, fat mass, hypertension, insulin, triglycerides and ALT." (PMID 36218092, 2022). "Thyroid-stimulating hormone (TSH), a hormone that primarily regulates the metabolism of the thyroid, has been associated with glycemic control and cardiovascular events partly explained by dyslipidemia, hypertension, and insulin sensitivity." (PMID 36419168, 2022). "The DASH diet pattern was already established as a potential treatment for hypertension, to reduce both fasting and postprandial insulin concentrations, and CRP levels." (PMID 35276919, 2022). "Due to the complexity and inaccessibility of performing insulin and C-peptide release assays, a simple indicator that recognizes early IR would be beneficial for substantial clinical hypertension management." (PMID 36035963, 2022).
Hypertension (continued). "This association remains significant after adjustment for confounding factors, as age, sex, hypertension, BMI, fasting plasma glucose, insulin, animal protein intake and renal function." (PMID 35748644, 2022). "The CgA-KO mice display two opposite aging phenotypes: hypertension but heightened insulin sensitivity at young age, whereas the blood pressure normalizes at older age and insulin sensitivity further improves." (PMID 36440192, 2022). "In comparison, aging WT mice gradually lost glucose tolerance and insulin sensitivity and developed hypertension." (PMID 36440192, 2022). "A total of 26% of the patients in the sample were diabetic on therapy with either an oral agent or insulin therapy (12.8% and 13.2%, respectively), while 54.3% had hypertension requiring pharmacologic treatment." (PMID 36357432, 2022). "In females, the variables with downtrend relative to increasing SMI quartiles were age, fat mass, hypertension, insulin, glucose, triglycerides and ALT." (PMID 36218092, 2022). "MUO describes as lower level of insulin sensitivity, higher concentrations of systematic inflammation, high prevalence of hypertension, and hypertriglyceridemia." (PMID 36660267, 2022). "Heterogeneous nuclear ribonucleoprotein can mediate insulin-driven inhibition of renal angiotensinogen gene expression and prevent hypertension and kidney injury in diabetic mice." (PMID 36140769, 2022). "The association remained statistically significant after multivariable adjustment for BMI, hypertension, glucose, and relevant lipid-related biomarkers, as well as after adjustment for plasma insulin and C-peptide." (PMID 35887628, 2022). "Similar results were found in the predictive role of the TyG, VAI, LAP, TyG-BMI, and TyG-WC in hypertension, suggesting that for young individuals, the combination of lipid and insulin parameters has the ability to predict hypertension." (PMID 36277749, 2022). "Mechanistic studies suggested that excess sympathetic activity promotes arterial hypertension while worsening insulin sensitivity." (PMID 36711125, 2022). "Malignancy, along with other risk factors including ethanol use, current smoker, DM requiring insulin therapy, hypertension requiring medication and a BMI less than 18.5 or ≥ 40 kg/m2 increase the incidence of unanticipated early postoperative re-intubation." (PMID 35055366, 2022). "The best predictive model for females was composed of RBP4, SCr, hypertension, log insulin, and log hs-CRP (AUC: 0.824, 95% CI: 0.796–0.852, Youden’s index: 0.510, P<0.001)." (PMID 35846279, 2022). "For most of the women with T1DM, we also had knowledge of their glycemic regulation pregestationally and during the pregnancy as well as average daily amount of insulin, hypertension status, and level of albuminuria." (PMID 36138412, 2022). "The variables including urine glucose, sweet flavor, pulse pressure, age, creatinine, heart rate, waist circumference, insulin, uric acid, and hypertension were the top-ten selected features." (PMID 36572938, 2022). "Users with hypertension (B=25.27, t=2.57, P=.02) and insulin treatment (B=18.17, t=3.02, P=.003) showed increased monthly average BG levels." (PMID 35133284, 2022). "After controlling for demographic variables, it was found that people with hypertension who displayed SB had lower insulin sensitivity and greater insulin resistance." (PMID 36554675, 2022). "Findings such as swelling, hypertension, insulin resistivity, insufficient insulin production, pancreatic cell collapse, and immoderate glucose release foreground DM." (PMID 36144587, 2022). "For the subgroup stratified by age, gender, BMI, hypertension, hyperlipidemia, anti-inflammation therapy, and insulin use, a significant relationship of SII with DKD was detected in each subgroup (all p< 0.05)." (PMID 36561561, 2022). "To find potential effect modifications, we tested for interactions by sex, age, BMI, eGFR, UAE, FPG, insulin, and hypertension." (PMID 35887628, 2022).
Hypertension (continued). "Previously, we demonstrated that the MetS mouse model also exhibits elevated plasma insulin level while others have reported elevated blood glucose and hypertension." (PMID 35933425, 2022). "Previous studies have shown that non-insulin-based IR indexes are associated with multiple risk factors of cardiovascular disease (CVD), such as hypertension, diabetes, obesity, and metabolic syndrome, and they also predict the incidence and prognosis of CVD." (PMID 35966520, 2022). "Pathophysiological mechanisms contributing to the relationship between abnormal lipid profiles and elevated risk of hypertension mainly involve the dysfunction of vascular endothelium, RAAS activation, and insulin resistance." (PMID 36246874, 2022). "In total, 34% of the participants used diabetic medications (oral hypoglycemics or insulin), nearly one-third (29%) used medications for hypertension, and fewer than 5% used steroids, antibiotics, or anticoagulants before admission." (PMID 35964951, 2022). "The links between hyperinsulinaemia and hypertension is thought to be driven via a few key mechanisms, (i) a decrease in insulin sensitivity, (ii) insulin mediated glucose disposal, both of which are thought to promote hypertension and atherogenesis." (PMID 36364763, 2022). "ACEIs and ARBs consistently and significantly reduce the incidence of T2D when used in patients suffering from hypertension or congestive heart failure, likely because of an improvement of insulin secretion and insulin sensitivity." (PMID 35742943, 2022). "After additional adjustment for BMI, WC, HbA1C, and TG (model 2), plus DM duration, history of hypertension, smoking and drinking history, insulin therapy, anti-hypertension drugs, and hypoglycemic therapy (model 3), this trend was retained." (PMID 36246918, 2022). "They found inversely cross-sectional associations between the adherence to this index with cardio-metabolic outcomes (such as hypertension, fasting blood glucose, fasting blood insulin, and cholesterol)." (PMID 36145237, 2022). "In the present review, we cover the potential roles and mechanisms by which MR activation impairs vascular insulin metabolic signaling and subsequently impacts the development of excessive vascular stiffening and hypertension." (PMID 36012219, 2022). "After adjustment for insulin, metformin, and antihypertensive treatment, drinking, smoking, BMI, hypertension, diabetic duration, age, gender in Model 1, the results remained consistent with the Crude model (p < 0.01)." (PMID 35842724, 2022). "Ferulic acid possesses beneficial health effects against oxidative stress, hypertension and late-stage diabetes in obese rats, as well as significantly improving insulin sensitivity and lipid profiles and reducing elevated blood pressure." (PMID 35567133, 2022). "As a less direct mechanism, higher fibre intakes improved insulin sensitivity in this and previous works, with insulin sensitivity believed to play a role in endothelial dysfunction and hypertension." (PMID 35449060, 2022). "From a clinical perspective, health care providers should encourage patients with hypertension to lose weight greater than 2 kg and also follow a lifestyle that prevents chronic elevated insulin levels and cardiac autonomic dysregulation." (PMID 35406053, 2022). "We performed a comprehensive comparison of non-insulin surrogate IR indices and their insulin-based parameters to determine their ability to predict the presence of hypertension." (PMID 36277749, 2022). "Metformin use has been shown to reduce fasting insulin levels and low-density lipoprotein, along with hypertension in PCOS." (PMID 36299963, 2022). "This was despite a higher prevalence of T2DM, hypertension and dyslipidaemia as well as greater medication burden including insulin treatment in this study." (PMID 35267942, 2022).
Hypertension (continued). "Several pathophysiological mechanisms impair insulin signaling in hypertension, such as renin–angiotensin, sympathetic nervous systems, and oxidative stress." (PMID 35455055, 2022). "Among its various functions, IGF-I protects against inflammation, hypertension, endothelial and β-cell dysfunction, inhibits growth hormone hypersecretion and suppresses insulin secretion whilst enhancing insulin's action." (PMID 35528832, 2022). "Regarding the non-insulin-based index reflecting IR, the TyG-BMI and TyG-WC performed better in predicting hypertension in females than in males in the current study." (PMID 36277749, 2022). "Variables including age, sex, ASA status, hypertension, preoperative hemoglobin, preoperative total bilirubin, preoperative oral hypoglycemics, preoperative insulin, surgical category, and emergency surgery were matched in PSM." (PMID 36337712, 2022). "The aim of this study was to examine the relationships between serum 25(OH)D levels and glucose tolerance and insulin sensitivity in hypertension." (PMID 35057492, 2022). "Using propensity score matching, participants were matched on factors including age, race, hypertension, coronary artery disease, insulin use, HbA1c, creatinine, BMI, and total number of anti-diabetic medications (not shown)." (PMID 36440189, 2022). "After feature selection, we obtained 16 features including γGT, AST, SBP, eGFR, age, HbA1c, FBG, duration, follow-up time, insulin, diuretic, statins, fibrates, hypertension, smoking status, and drinking status." (PMID 35655800, 2022). "Patients who were using insulin only were less likely (OR = 0.5 (95% CI: 0.2, 0.9); p-value 0.026) to have uncontrolled hypertension compared to those who were on oral hypoglycemic agents only." (PMID 34917355, 2022). "High blood pressure is correlated with lower insulin sensitivity leading to impaired glucose uptake." (PMID 36536959, 2022). "The prevalence of comorbidities such as hypertension, coronary artery disease, heart failure, stroke, and chronic kidney disease was higher among insulin users, except that of hyperlipidemia." (PMID 34457016, 2021). "In order to study the effects of the process of aging on vascular endothelial dysfunction in hypertension, the insulin- and IGF-1-mediated vasorelaxation was evaluated in endothelium-intact and denuded rings among the four groups." (PMID 34203897, 2021). "For example, patients in the dapagliflozin group had blood pressure readings consistent with grade 1 hypertension while blood pressure values in the insulin group were similar to those of controls." (PMID 33592103, 2021). "This is through enhancing insulin sensitivity within the nucleus of the solitary tract to prevent hypertension by increasing nitric oxide production." (PMID 33613184, 2021). "Insulin is responsible for vasodilatation through nitric oxide (NO) production, and in reverse, IR stimulates vasoconstriction, leading also to hypertension." (PMID 33921359, 2021). "In the multivariate analysis, after controlling for the variables age, HbA1c, years since diagnosis, hypertension, and both metabolites of vitamin D, the OR was 5.76 (95% CI: 1.16, 28.69; p = 0.033) for human insulin." (PMID 35010958, 2021). "Upon univariate analysis, we found that age, hypertension, hyperlipidemia, insulin therapy, and ethnicity were correlated with presence of asymptomatic LVDD." (PMID 34646868, 2021). "Of the patients, 13 out of 39 patients (33.3%) satisfied the criteria for MetS+, 19 out of 39 individuals (48.7%) were insulin resistant, 28 out 39 (71.8%) had hypertension, 7 out of 39 (18%) were obese, and 15 out of 39 (38.5%) were overweight." (PMID 34579044, 2021). "On the other hand, α-Lipoic acid improves insulin sensitivity and prevents hypertension in rats fed a high fructose diet for 20 days." (PMID 35153813, 2021).
Hypertension (continued). "Consistently, we found that the coexistence of aging and hypertension induced more severe endothelial dysfunction in response to insulin and IGF-1 in older SHRs." (PMID 34203897, 2021). "Visceral fat that accumulates around individual internal organs decreases body sensitivity to insulin, which contributes to oxidative stress, inflammation, vascular endothelial dysfunction, and hypertension." (PMID 34575650, 2021). "The transcription factor PPARγ also modulates insulin sensitivity and hypertension through its anti-inflammatory and vasodilatory actions." (PMID 34966295, 2021). "All these findings suggest a role of insulin-induced ET-1 predominance in the development of hypertension." (PMID 34966295, 2021). "We found that SWS sleep duration was independently associated with insulin level, similar to a previous study reporting that decreased SWS was associated with a dose-dependent increase in OSA-associated hypertension." (PMID 33658975, 2021). "MHO are obese subjects with a favorable metabolic profile with the absence of metabolic complications including inflammation, dyslipidemia, and hypertension, and preserved insulin sensitivity despite excessive body fatness." (PMID 34948944, 2021). "The enterotype 2 seems to correlate with hypertension, rheumatoid arthritis, and insulin sensitivity." (PMID 34835466, 2021). "Multivariable Cox proportional hazard analysisAge, gender, co-morbidities (Ischaemic heartdisease, cardiovascular disease, hyperlipidaemia,chronic renal disease, hypertension), insulin use." (PMID 33763024, 2021). "We further explored the association between weight change and risk of ESRD after stratification by age, sex, presence of proteinuria, history of hypertension, BMI, number of oral hypoglycemic agents, insulin use, and DM duration using subgroup analyses." (PMID 35011029, 2021). "Intake of caffeine improves fructose-induced insulin resistance and hypertension by enhancing central insulin signaling in rats." (PMID 33613184, 2021). "In the current study, neither the mHFD nor the mCD10d offspring group responded with changes in MAP or RSNA when the InsR antagonist was administered ICV or into the VMH suggesting little role of insulin in mediating the hypertension or sympatho-excitation." (PMID 34248679, 2021). "This study aimed to investigate the aging-related endothelial dysfunction mediated by insulin and insulin-like growth factor-1 (IGF-1) and antioxidant deficiency in hypertension." (PMID 34203897, 2021). "The Prevotella cluster has, instead, been correlated with hypertension, rheumatoid arthritis, insulin-sensitivity, and HIV infections, especially when intercepted in male homosexuals." (PMID 34835466, 2021). "Multivariable analysis suggested hypertension-resistin-HbA1c interactions associated with SAT’s larger adipocytes; whereas potential insulin-adiponectin associations were observed for VAT’s larger adipocytes." (PMID 33469087, 2021). "Another possible mechanism is that the impairment in the uptake of glucose due to delivery alteration of insulin and glucose to skeletal muscle by insulin resistance increased in patients with hypertension." (PMID 33546150, 2021). "Dark chocolate showed the highest effect for BMI and high blood pressure, and treatment with insulin increased weight in those with T2D." (PMID 34805192, 2021). "The excess of circulating metabolically active compounds such as glucose, insulin, FFA, and leptin in obese women is likely to increase the risk of hypertensive disorders of pregnancy." (PMID 33869631, 2021). "Dietary fructose has been shown to induce increased body fat and weight, hyperlipidemia, hypertension, glucose intolerance, and decreased insulin sensitivity, with fructose combining fat and carbohydrate deregulation in both humans and animals." (PMID 32206470, 2020). "The antinatriuretic properties of insulin which increases renal retention of sodium also aids in the development of hypertension." (PMID 32968405, 2020).